RFC1 (replication factor C subunit 1)
Diseases named in the same sentence as RFC1 in open-access papers (continued):
Sharing a sentence is not in itself a finding about the gene and the disease.
cerebellar ataxia (continued). "Among 27 patients with cerebellar ataxia and SG diagnosed with coeliac disease or gluten sensitivity, 15% had RFC1 expansions." (PMID 37414537, 2024). "More recently, intronic repeat expansions in RFC1 (cerebellar ataxia, neuropathy, and vestibular areflexia syndrome, CANVAS) and FGF14 (SCA27B) have been identified as more significant causes of adult-onset ataxia than previously appreciated." (PMID 38132285, 2023). "PD associated with GBA1, SNCA and RFC1 has been reported in north Karelia, where the author also diagnosed a family with POLG2-associated PD (POLG2-mutations have been observed also in ataxia patients in the region; all data are unpublished)." (PMID 37373667, 2023). "We examined 1,289 Japanese patients with cerebellar ataxia and analyzed RFC1 repeat expansions in 840 patients, excluding those with genetic diagnoses or an autosomal dominant inheritance pattern." (PMID 36034314, 2022). "In 2019, the RFC1 biallelic AAGGG intronic repeat expansion was identified in patients with CANVAS with late-onset ataxia." (PMID 36034314, 2022). "In this study, we analyzed RFC1 repeat expansions in a large case series of Japanese patients with cerebellar ataxia and describe the clinical and genetic features of 15 patients harboring biallelic RFC1 pathogenic repeat expansions." (PMID 36034314, 2022). "We conducted this study to demonstrate the clinical and genetic features of a large-scale case series of Japanese patients with cerebellar ataxia with RFC1 repeat expansions." (PMID 36034314, 2022). "In conclusion, we describe multitype RFC1 repeat expansions in 1.8% (15/840) of undiagnosed patients with cerebellar ataxia and sporadic/recessive/unclassified inheritance." (PMID 36034314, 2022). "Pathological RFC1 repeat expansions account for 1.8% (15/840) of undiagnosed patients with cerebellar ataxia and sporadic/recessive/unclassified inheritance." (PMID 36034314, 2022). "As yet, the exact incidence of RFC1-associated neurological diseases remains uncertain although first studies suggest that RFC1-related ataxia is common." (PMID 38835435, 2021). "We have also optimised a protocol for RFC1 expansion screening which is described herein and expanded phenotype after analysing late-onset ataxia patients from around the world." (PMID 32910249, 2021). "Expansion in ATXN8/OS results in the majority of dominant ataxias in Finland, while mutations in RFC1 and POLG are the most common cause of recessive ataxias." (PMID 34600502, 2021). "Unidentified RFC1 disease is still frequent among patients with unsolved ataxia, as indicated by our 2 screening cohorts, highlighting the need for additional clinical and genetic identification strategies." (PMID 33495376, 2021).
cerebellar ataxia (continued). "Subsequently, other phenotypes such as ataxia with chronic cough, incomplete CANVAS and MSA-C-like phenotypes have been associated with biallelic RFC1 repeat expansions." (PMID 38835435, 2021). "For CANVAS / RFC1-related ataxia, quantitative data on other oculomotor biomarkers is scarce." (PMID 40111638, 2025). "vHIT is a potential biomarker for monitoring progression of CANVAS/RFC1-related ataxia." (PMID 40111638, 2025). "We hypothesized that most patients with CANVAS / RFC1-related ataxia will demonstrate significantly reduced aVOR-gains at the time of initial testing with further deterioration over time." (PMID 40111638, 2025). "Notably,RFC1-related ataxia emerged as the most prevalent form within the cohort, closely followed by variants inKIF1AandSYNE1." (PMID 40360003, 2025). "Thus, vHIT is the preferred cross-sectional and also longitudinal quantitative oculomotor biomarker in CANVAS/RFC1-related ataxia." (PMID 40111638, 2025). "Although the pathophysiology of CANVAS/RFC1-related ataxia is not fully understood, evidence from post-mortem studies suggest that it is caused by a neuronopathy (ganglionopathy) that affects the Scarpa’s ganglion (but spares the spiral ganglion) and the dorsal root ganglion." (PMID 40111638, 2025). "For neurodegenerative disorders such as CANVAS/RFC1-related ataxia, the ability to detect aVOR-deficits at early stages of vestibulopathy could allow for earlier disease detection and monitoring of progression." (PMID 40111638, 2025). "The current study demonstrates that in a patient with ataxia the absence of SG virtually excludes RFC1 expansion as the cause of the ataxia." (PMID 37414537, 2024). "We wanted to clarify if RFC1 expansions can present with pure ataxia and if such expansions could be responsible for some cases where an alternative diagnosis had been made." (PMID 37414537, 2024). "Whereas for certain disorders such as FRDA, SCA2, SCA3, SCA6, and A-T, we were able to retrieve descriptions of oculomotor abnormalities for a broad range of paradigms, in other disorders such as AOA1/2, NPC, or RFC1-related ataxia previous studies focused on only a limited number of paradigms." (PMID 36640220, 2024). "Importantly, CANVAS, a relatively common AR ataxia due to STR expansions in RFC1, has been subsequently added to the list, and will be discussed in detail in the next section." (PMID 38760634, 2024). "We discuss genetic forms of ataxia related to recently discovered genes or gene variant types, including STR expansions in RFC1 (CANVAS), FGF14 (SCA27B) and THAP11 (‘SCA51’), as well as discussing SCA4, for which the genetic basis has only recently been discovered." (PMID 38760634, 2024). "From a clinical perspective, screening patients with the combination of cerebellar ataxia (the initial presenting complaint) and SG in the absence of any other cause has a diagnostic yield of 71% for RFC1 expansion." (PMID 37414537, 2024). "RFC1-related cerebellar ataxia has also been reported to occur at <10 years of age." (PMID 36034314, 2022).
cerebellar ataxia (continued). "With the discovery of biallelic expansion in the replication factor C subunit 1 (RFC1) gene as its underlying genetic cause, this syndrome and the broader gene disease became more clinically heterogeneous and one of the most common genetic causes of ataxia in adults." (PMID 41145152, 2025). "However, it must be noted that not all patients with a CANVAS phenotype have repeat expansions (or rare truncating mutations) in the RFC1 gene and not all patients demonstrate the full spectrum of RFC1-related ataxia." (PMID 40111638, 2025). "Therefore, we screened the RFC1 expansion in Canadian and Brazilian ataxia patients." (PMID 31824583, 2019). "The remaining ataxias (FRDA, RFC1-related ataxia, EA2, SCA2, SCA3, SCA6, and SCA27B) all had instead at least two studies in which vestibular testing results were included." (PMID 40801974, 2025). "For most other ataxias studied, scores were 3 or lower on all domains (SCA1, SCA7, EA2, RFC1-related ataxia, AOA1, AOA2, CTX, SCA27B)." (PMID 40801974, 2025). "While the evidence on the use of vHIT in CANVAS / RFC1-related ataxia is growing, patient numbers per study are often small and a more detailed characterization of vHIT patterns in CANVAS / RFC1-related ataxia is missing." (PMID 40111638, 2025). "In our large cohort of 3000 patients with ataxia, CANVAS due to RFC1 expansions was the third most common autosomal recessive (AR) ataxia after Friedreich’s ataxia (FA; 28%) and spastic paraplegia type 7 (SPG7) (14%), accounting for 11% of all AR ataxias." (PMID 37414537, 2024). "With 3.8% of ataxia patients, 8% of neuropathy patients, 31.1% of ataxia with neuropathy patients and 35.7% of clinically suspected patients with CANVAS harbouring biallelic RFC1 expansions." (PMID 37621409, 2023). "This is the first study to examine the RFC1 intronic repeat region in a historically collected putative Dutch CANVAS and two adult-onset ataxia cohorts and use optical genome mapping (Bionano Genomics) to determine the size of the expanded RFC1 repeat length." (PMID 35864213, 2022). "RFC1-positive patients were not more likely to have been investigated for ataxia—only one of the five RFC1-positive patients had had an MRI and that was for investigation of possible epilepsy—and the MRI was normal." (PMID 41322202, 2025). "Sensory neuropathy appears to be a core feature of the condition, leading many to regard ‘RFC1 spectrum disorder’ as a ‘neuropathy plus’ rather than an ‘ataxia plus’ syndrome." (PMID 41322202, 2025). "Our study demonstrates that FGF14 GAA repeat expansions are common in patients negative for biallelic RFC1 repeat expansions presenting with a combination of cerebellar ataxia plus polyneuropathy and/or BVP." (PMID 37399286, 2024). "We have also screened for biallelic RFC1 expansions in two patients prior to confirmation of paraneoplastic cerebellar ataxia and SG, both of whom were negative." (PMID 37414537, 2024). "Our main aim in this study was to clarify if patients with RFC1 expansions can present with pure ataxia in the absence of SG or any other form of peripheral nerve involvement." (PMID 37414537, 2024). "We recruited 45 patients negative for biallelic RFC1 repeat expansions with a combination of cerebellar ataxia plus peripheral neuropathy and/or bilateral vestibulopathy (BVP), and genotyped the FGF14 repeat locus." (PMID 37399286, 2024).
cerebellar ataxia (continued). "This allows for all ataxia and neuropathy samples that are tested on the targeted gene panels to be concurrently screened for the RFC1 expansion, without additional testing being conducted on the sample." (PMID 37621409, 2023). "Screening of RFC1 repeat expansions should be considered in patients with cerebellar ataxia, irrespective of their subtype and onset age." (PMID 36034314, 2022). "Afferent ataxia (i.e., marked worsening of gait ataxia without visual control), sensory symptoms, and chronic cough not only were more common in RFC1-positive patients but also yielded a positive predictive value of >90%." (PMID 33495376, 2021). "In one of the largest studies performed so far, RFC1 expansions were identified in ∼92 % of patients with a full CANVAS phenotype, ∼63 % of patients with ataxia and neuronopathy and ∼22 % of patients with ataxia only." (PMID 38835435, 2021). "We also confirm that even if patients are examined thoroughly and prospectively, RFC1-positive patients may not show signs of ataxia or vestibulopathy but may be more likely to have autonomic symptoms." (PMID 41322202, 2025). "Importantly, we have shown for the first time that RFC1 expansions are highly unlikely in cases with isolated cerebellar ataxia and in the absence of SG." (PMID 37414537, 2024). "In conclusion, we showed that FGF14 GAA repeat expansions are a common cause of cerebellar ataxia plus polyneuropathy and/or BVP in patients negative for biallelic RFC1 repeat expansions, thus expanding the phenotypic spectrum of this recently described disorder." (PMID 37399286, 2024). "Accordingly, no patient with pure DBN or DBN plus cerebellar impairment (without BVP and/or polyneuropathy) was found to carry biallelic RFC1 repeat expansions, strengthening the observation that RFC1-related disorder is unlikely in presence of isolated cerebellar ataxia without sensory neuropathy." (PMID 38381176, 2024). "We performed here the first systematic analysis of clinical features that might allow discriminating RFC1-positive from RFC1-negative ataxia." (PMID 33495376, 2021). "The co-occurrence of ataxia with autonomic dysfunction, bradykinesia, and even features of REM sleep behavior disorder not only overlaps with MSA-C phenotypes but even formally meets the diagnosis criteria of possible MSA22 (while RFC1, of course, does not cause pathologically confirmed MSA23)." (PMID 33495376, 2021). "Here, we studied the frequency of FGF14 GAA repeat expansions in patients with a combination of cerebellar ataxia plus peripheral neuropathy and/or BVP negative for biallelic RFC1 repeat expansions, and report on the phenotypic spectrum of GAA-FGF14-positive patients." (PMID 37399286, 2024). "We investigated 569 Finnish patients with medicated parkinsonism for RFC1 and found biallelic (AAGGG)exp in three non-consanguineous patients with clinically confirmed Parkinson’s disease without ataxia suggesting that RFC1-related disorders include Parkinson’s disease as well." (PMID 35013364, 2022).
neuropathy (58 papers, 2020 to 2026). A disorder affecting the nervous system that manifests with pain, tingling, numbness, and/or muscle weakness. "Their findings highlight the importance of clinical assessment and consideration of investigation findings to differentiate RFC1-associated neuropathy from immune-mediated neuropathy, a distinction of high clinical relevance given the therapeutic implications." (PMID 38978727, 2024). "Though many cohorts have assessed the prevalence of RFC1 pathogenic expansions within late-onset ataxia cohorts, fewer have screened neuropathy-only cohorts." (PMID 37621409, 2023). "Their findings may be attributed to differences in clinical presentation of RFC1-associated neuropathy compared to immune-mediated neuropathy." (PMID 38978727, 2024). "The underlying pathophysiology of RFC1-associated neuropathy remains unknown." (PMID 38978727, 2024). "Further studies into the pathogenesis of RFC1-mediated neuropathy will provide insights into the mechanisms of disease and the implications for heterozygous carriers." (PMID 38978727, 2024). "Therefore, it is unclear if carriers of pathogenic RFC1 expansions could be at risk of neuropathy." (PMID 38978727, 2024). "RFC1-related neuropathy is often accompanied by chronic cough and autonomic disturbance, which are suggestive signs of RFC1-related disorders among IPNs." (PMID 35884855, 2022). "Accordingly, pathology records described an involvement of large, small MF and unmyelinated nerve fibers, respectively, in 100%, 97% and 85% of RFC1-positive patients, and 99%, 81% and 41% in other neuropathies." (PMID 33884451, 2021). "In addition, among the 20 patients with CANVAS/RFC1‐neuropathy, the length‐dependent EDX pattern was found in 8/20 (40%); in the 6 patients for whom SRAR was analyzed, the values were greater than 0.33." (PMID 41063615, 2026). "Its role as an adjunct to conventional criteria could be particularly useful in challenging cases such as early‐stage SNN, CANVAS/RFC1‐neuropathy, and atypical CIDP presentations." (PMID 41063615, 2026). "In all patients with CANVAS/RFC1‐neuropathy in whom a SRAR could be calculated in the current series, SRAR was > 0.33, suggesting its complementary role to the Camdessanche criteria." (PMID 41063615, 2026). "Acquired causes for neuropathy were identified in 10 of the 38 patients with negative RFC1 testing: this highlights the need for reconsidering the diagnosis where no cause has been found." (PMID 41322202, 2025). "In this case, the only feature suggesting a RFC1-related disorder was incipient neuropathy." (PMID 39416949, 2024). "This has implications for treatment and may be relevant in individuals with known RFC1 neuropathy who may be progressing faster than expected, or in individuals with diagnosed immune-mediated neuropathy who stop responding to treatment." (PMID 38978727, 2024). "Biallelic RFC1 mutations were found in three patients with immune-mediated neuropathies, including Guillain-Barré syndrome, idiopathic sensory ataxic neuropathy, or anti-myelin-associated glycoprotein (MAG) neuropathy, who responded to immunotherapies." (PMID 37853169, 2023). "SRAR may be useful in SNN, particularly in CANVAS/RFC1‐neuropathy." (PMID 41063615, 2026). "Furthermore, it suggests that we should not exclude participants with diabetes when considering RFC1 as a potential cause of neuropathy, especially in the presence of a cough." (PMID 41322202, 2025). "Accordingly, the current study examined RFC1 in 240 patients with immune-mediated neuropathy, such as GBS, CIDP, and MAG neuropathy, as well as other types of neuropathies." (PMID 37853169, 2023).